CDC25A (cell division cycle 25A)
Diseases named in the same sentence as CDC25A in open-access papers (continued):
Sharing a sentence is not in itself a finding about the gene and the disease.
gastric cancer (11 papers, 1999 to 2025). A primary or metastatic malignant neoplasm involving the stomach. "We analysed the expression level and tumour stemness index relationship and chose CDC25A as our research subject to investigate its expression, mutational landscape and functional enrichments in gastric cancer." (PMID 38613794, 2024). "These experimental findings provide compelling evidence that CDC25A possesses the capacity to modulate both cell proliferation and tumor stemness in the gastric cancer." (PMID 38613794, 2024). "In the final phase of our investigation, CDC25A emerged as a focal point for in-depth exploration through in vitro experimentation, aimed at corroborating its impact on gastric cancer cells and tumor stemness." (PMID 38613794, 2024). "In light of the bioinformatic analyses conducted, in vitro studies were carried out to verify the effects of CDC25A on gastric cancer cell proliferation, cell cycle, and tumor stemness." (PMID 38613794, 2024). "The CCK8 experimental findings indicated that suppressing CDC25A expression led to a noteworthy decline in the viability of gastric cancer cells by 0.4467 ± 0.1209 at 48 h." (PMID 38613794, 2024). "We conducted assays on cell activity, cell cycle and immunofluorescence to confirm the function of CDC25A in gastric cancer, with specific focus on cell proliferation, cell cycle and tumour stemness." (PMID 38613794, 2024). "To elucidate the specific biological role of CDC25A within gastric cancer pathways, we conducted an enrichment analysis." (PMID 38613794, 2024). "Bioinformatics analyses unveil CDC25A’s implication in driving the malignant phenotype of tumors, with a discernible impact on cell proliferation and DNA replication in gastric cancer." (PMID 38613794, 2024). "Remarkably, our findings revealed that the suppression of CDC25A expression in gastric cancer cells elicited a notable reduction in cellular viability and proliferation." (PMID 38613794, 2024). "In human gastric cancer cells, melatonin induced cell cycle arrest and downregulated CDC25A, phospho-CDC25A, and p21." (PMID 39764218, 2024). "To explore the impact of CDC25A on tumor stemness within gastric cancer, we selected CD44 as a well-established marker for cancer stemness investigation." (PMID 38613794, 2024). "Noteworthy validation through in vitro experiments corroborated the bioinformatics findings, elucidating the pivotal role of CDC25A expression in modulating tumor stemness in gastric cancer." (PMID 38613794, 2024). "The SNHG11/miR-184/CDC25A ceRNA network is a new biomarker for the diagnosis, treatment and prognosis of gastric cancer." (PMID 34966747, 2021). "In gastric cancer cells, ART-mediated apoptosis was associated with down-regulation of CDC25A and Bcl-2 and up-regulation of Bax accompanied by reduced mitochondrial membrane potential levels." (PMID 33316936, 2020). "MEL causes cell cycle arrest and suppression of CDC25A, phospho-CDC25A (at Ser75), p21 (p21Cip1/p21Waf1) and phospho-p21 (at Thr145) expressions in SGC-7901 gastric cancer cell line." (PMID 30563247, 2018). "Apart from its regulatory role in the NF-κB pathway, USP47 constitutes an interesting target for gastric cancer chemotherapy, because it promotes gastric carcinoma cell proliferation, and its depletion sensitize cancer cells to chemotherapy, probably due to the upregulation of Cdc25a." (PMID 29786670, 2018). "Delayed down-regulation of Cdc25A and cdk4 may contribute to cell adaptation to the quiescent state in the two gastric carcinoma cell lines studied." (PMID 10376964, 1999). "Using two TGF-β-sensitive gastric carcinoma cell lines (SNU-16 and -620), we addressed the contributory roles of several cdk inhibitors, and of cdk4 and Cdc25A, in TGF-β-induced cell cycle arrest by comparing their temporal expression pattern in response to TGF-β." (PMID 10376964, 1999).
glioblastoma (11 papers, 2012 to 2025). The most malignant astrocytic tumor (WHO grade IV). "Additionally, Cdc25A appears to be a promising therapeutic target in glioblastomas as its levels were reported to correlate with Ki-67 labeling index." (PMID 23358700, 2013). "In addition, we identify positive correlations among Cdc25A Y59 phosphorylation, Cdc25A and PKM2 in human glioblastoma specimens." (PMID 27485204, 2016).
ovarian carcinoma (11 papers, 2002 to 2024). A malignant neoplasm originating from the surface ovarian epithelium. "It predominantly inhibited ovarian cancer cells by inducing G0/G1 cell cycle arrest via suppressing the c-Myc/Cdc25A pathway." (PMID 34065149, 2021). "Trichodermin down-regulated the expression of Cdc25A in both ovarian cancer cell lines, which hampered the G1/S transition and resulted in the G1 cell cycle arrest." (PMID 34065149, 2021). "PRKAR2A-rearrangements have been reported as an in-frame CDC25A-PRKAR2A fusion in the TCGA ovarian cancer data set." (PMID 28893231, 2017). "Overexpression of CDC25A has been reported in breast, esophageal, hepatocellular, colorectal and ovarian carcinomas." (PMID 20500813, 2010). "A study have shown that CDC25A promotes resistance to cisplatin and paclitaxel in ovarian cancer." (PMID 39830513, 2024). "CDC25A is a cell cycle and apoptosis regulator that plays a vital role in many cancers’ progression, for example, breast, esophageal, lung, colorectal, prostate, and ovarian cancer." (PMID 35887528, 2022). "A CDC25A-PRKAR2A fusion was previously reported in an ovarian carcinoma." (PMID 28893231, 2017). "However, in oesophageal carcinoma, similar to our results, cdc25A was accumulated both in cytoplasms and nuclei, and in ovarian carcinoma, its immunoreactivity was seen mainly in cytoplasms, indicating that the localisation of this phosphatase depends on the origin of the carcinoma." (PMID 12085185, 2002). "Knock down of SMYD3 in ovarian cancer tissues leads to upregulation of CDKN2B (p15INK4B), CDKN2A (p16INK4), CDC25A and CDKN3 as members of cyclin-dependent kinase inhibitors (CDK)." (PMID 33333978, 2020). "CDC25A was significantly overexpressed (p=0.02) and BIRC3 was significantly down-regulated (p=0.02) after SMYD3 knockdown in ovarian cancer PDX model." (PMID 31417652, 2019).
prostate carcinoma (11 papers, 2012 to 2024). A carcinoma that arises from epithelial cells of the prostate gland. "Similar to the silencing of CDC25A, reevesioside A induced a profound down-regulation of CDC25A, cyclin D1 and cyclin E, facilitating G1 arrest of the cell cycle in prostate cancers." (PMID 24475272, 2014). "In addition, NSC95397 (20 μm) was previously shown to accelerate CDC25A degradation via the proteasome pathway in two human prostate cancer cell lines, PC‐3 and LNCap." (PMID 33048473, 2020). "In prostate cancers, CDC25A inhibitors were used and found to inhibit the downstream activation of MEK with CDC25A directly." (PMID 38313315, 2024). "Other target genes such as CDC25A, mTOR were not affected, although miR-100 was reported to cooperate with other factors to down-regulate mTOR pathway in prostate cancer." (PMID 31293973, 2019). "Moreover, after X‐ray irradiation, Tip60 knockdown significantly decreased the survival of prostate cancer cells, reduced the acetylation of ATM and decreased the phosphorylation levels of AKT, Chk2 and cdc25A." (PMID 29435417, 2018). "Furthermore, Tip60 may modulate the survival of irradiated prostate cancer DU145 and LNCaP cells via activating the ATM/Chk2/cdc25A pathway." (PMID 29435417, 2018).
lung adenocarcinoma (9 papers, 2016 to 2025). A carcinoma that arises from the lung and is characterized by the presence of malignant glandular epithelial cells. "Higher expression of CDC25A protein has been observed in lung adenocarcinoma cells than in normal lung fibroblasts." (PMID 34363019, 2022). "A traditional Chinese medicine Ganoderma tsugae has been observed to induce S phase arrest of lung adenocarcinoma cells by suppressing CDC25A and inactivating the PI3K/AKT signaling pathway." (PMID 34266408, 2021). "High expression of YBX1 or CDC25a protein was also observed in lung adenocarcinoma cells compared with HLF cells." (PMID 27384875, 2016). "We further discovered positive correlation between YBX1 and CDC25a expression (R=0.223, p=0.016) in human lung adenocarcinoma." (PMID 27384875, 2016). "Simultaneously, high expression of YBX1 or CDC25a in 116 patients with lung adenocarcinoma had shorter 5-year overall survival than low expression (5-OS%:40.5% VS 74.9%, p=0.044 and 5-OS%:45.5% VS 79.7%, p=0.004, respectively)." (PMID 27384875, 2016). "All the evidence showed that the novel YBX1/CDC25a pathway is a potential therapeutic target for the treatment of human lung adenocarcinoma." (PMID 27384875, 2016). "The retrospective analysis of 116 patients with lung adenocarcinoma indicated that YBX1 was positively correlated with CDC25a expression." (PMID 27384875, 2016). "In our study, we assessed the expression of YBX1 and CDC25a in patients with complete with surgical resection of lung adenocarcinoma on basis of IASLC/ATS/ERS international multidisciplinary classification for the first time." (PMID 27384875, 2016). "In summary, YBX1 increases the promoter activity and expression of CDC25a in human lung adenocarcinoma cells." (PMID 27384875, 2016). "We analyzed the expression of YBX1 and CDC25a in 116 patients with complete surgical resection of lung adenocarcinoma by IHC staining." (PMID 27384875, 2016). "Furthermore, Zhao and colleagues demonstrated that endogenous YBX1 binds to the CDC25a promoter regions, leading to increased CDC25a promoter luciferase expression in human lung adenocarcinoma cells." (PMID 40799245, 2025). "Furthermore, we showed that endogenous YBX1 bound to the specific CDC25a promoter region in lung adenocarcinoma cells as compared to the HLF cells by ChIP assay." (PMID 27384875, 2016). "Then we demonstrated the hypothesis that CDC25a transcription activation was dependent on YBX1, which provided a new perspective mechanism on CDC25a expression regulation in lung adenocarcinoma." (PMID 27384875, 2016). "Therefore, it's essential to clarify how CDC25a is over-activated during malignant proliferation in lung adenocarcinoma." (PMID 27384875, 2016). "Next, we certified the assumptive mechanisms that YBX1 as the transcriptional activator to accelerate expression of CDC25a, and then the cell cycle, growth and apoptosis in human lung adenocarcinoma cells as well as the inhibition of YBX1 on the growth of xenografts in mice were tested." (PMID 27384875, 2016). "The multivariate analysis of risk factors showed that high TNM stage (HR=3.428, 95%CI: 1.519-7.737, p=0.003) and low CDC25a expression (HR=2.384, 95%CI: 1.008-7.642, p=0.048) were independent prognostic risk factors in lung adenocarcinoma but not YBX1." (PMID 27384875, 2016). "In addition, the expression of YBX1 and CDC25a from lung adenocarcinoma cells' total, nuclear and cytoplasm protein was also higher than HLF cells analyzed by Western blot assays." (PMID 27384875, 2016). "In line with uncontrolled cell cycle progression in SCLC, we find that CDC25A, B and C mRNAs are expressed at significantly higher levels in SCLC, compared to lung adenocarcinoma." (PMID 29138515, 2017). "In our present study, IHC staining was performed to show the expression of CDC25a and YBX1 in 116 patients with lung adenocarcinoma." (PMID 27384875, 2016).
lung adenocarcinoma (continued). "High CDC25a expression and TNM stage were significantly independent factors for predicting poor prognosis of patients with lung adenocarcinoma." (PMID 27384875, 2016). "utilized non-small cell LCOs to identify CDK1, CCNB2, and CDC25A as pivotal oncogenes in lung adenocarcinoma but not in lung squamous cell carcinoma." (PMID 37941550, 2023). "Knockdown of CDC25A did not impede the proliferation of lung adenocarcinoma cell lines, but effectively suppressed the growth of lung adenocarcinoma organoids." (PMID 37941550, 2023). "Another study about lung adenocarcinoma showed the similar results, and it revealed in vitro study that YB1 expression was closely related to cell cycle progression, cell proliferation apoptosis via the CDC25a pathway." (PMID 35260638, 2022).
pancreatic cancer (9 papers, 2013 to 2024). "According to previous reports, silencing Nuf2 by RNA interference can inhibit the proliferation of pancreatic cancer cells and cause cell cycle arrest in the G0/G1 phase by inhibiting Cyclin B1, CDC2, and Cdc25A." (PMID 35393397, 2022). "Recently, it was proposed that Hsp90ab1 might stabilize Cdc25A, increasing its expression levels and promoting cell-cycle activation in pancreatic carcinoma cells." (PMID 30305727, 2019). "The involvement of these targets of E2F7, such as BRCA1, CDC25A, CDC6 in pancreatic cancer deserves further investigation." (PMID 35201478, 2021).
non-small cell lung carcinoma (8 papers, 2016 to 2023). A group of at least three distinct histological types of lung cancer, including non-small cell squamous cell carcinoma, adenocarcinoma, and large cell carcinoma. "miR-365 strengthens radiosensitivity of non-small cell lung cancer (NSCLC) cells via targeting CDC25A." (PMID 35036112, 2022). "For example, over-expression of gene CDC25A, an oncogene, was significantly correlated with poor overall survival in non-small cell lung cancer." (PMID 28587642, 2017). "We recently reported that miR-184 promotes tumor progression in non-small cell lung cancer via targeting CDC25A and c-Myc." (PMID 27083050, 2016). "CDC25A overexpression was found in head and neck, breast, ovarian, and non-small cell lung cancer." (PMID 35625619, 2022).
liver cancer (7 papers, 2019 to 2025). An epithelial or non-epithelial malignant neoplasm that arises from the liver. "A study showed that inhibiting the activity of CDC25A may provide a new treatment for the control of liver cancer." (PMID 35513781, 2022). "Interestingly, we discovered that miR‐191 strongly and positively correlated with several important cell cycle regulators, including CDC25A, CDC7 and CDCA8 in the TCGA liver cancer database." (PMID 31334580, 2019).
sarcoma (6 papers, 2013 to 2022). A usually aggressive malignant neoplasm of the soft tissue or bone. "In parallel, Bertucci and colleagues reported a positive correlation between Wnt activation and expression of CDC25A mRNA in a large series of sarcoma patient samples." (PMID 32911761, 2020). "Recently, the authors have identified CDC25A as a Wnt transcriptional target, an important mediator of Wnt-induced sarcoma cell proliferation both in vitro and in vivo." (PMID 25999350, 2015). "In U2OS cells, SEN461, was shown to modulate the canonical Wnt transcriptional target AXIN2 toghether with CDC25A, recently described as an important mediator of Wnt-induced sarcoma cell proliferation both in vivo and in vitro." (PMID 24842792, 2014). "This new strategy could benefit sarcoma patients with molecular alterations in the Wnt signaling pathway, especially if CDC25A deregulation is observed." (PMID 32911761, 2020). "Accumulated data suggest that the Wnt signaling exerts its oncogenic functions via upregulation of target genes involved in cell proliferation, exemplified by the β-catenin/TCF transcriptional effects on c-Myc expression in carcinomas, and CDC25A recently identified in sarcomas." (PMID 25999350, 2015). "A major genetic network contains known cancer-related or pro-proliferating genes, including CDC25A, CDK19, FUS (fused in sarcoma), TLE3, and ILF3 (interleukin enhancer binding factor 3) was formed." (PMID 24160375, 2013).
esophageal squamous cell carcinoma (5 papers, 2001 to 2023). Esophageal squamous cell carcinoma (ESCC) is a type of esophageal carcinoma (EC) that can affect any part of the esophagus, but is usually located in the upper or middle third. "For example, miR-21 was highly expression in exosomes in ESCA, and anti-miR-21 inhibited the chemotherapy resistance of ESCA in vitro; exosome-derived miR-339-5p mediates radiosensitivity by targeting Cdc25A in locally advanced esophageal squamous cell carcinoma." (PMID 33146702, 2020).
neuroblastoma (5 papers, 2013 to 2024). Neuroblastoma (NB) is the most common solid, extracranial childhood tumor. "In this study, we observed that all-trans-retinoic acid (ATRA) treatment reduced the phosphorylation of CDC25A Ser18 in both neuroblastoma cell lines tested." (PMID 38256121, 2024). "CDC25A enhanced proliferation rate and promoted a more undifferentiated cell phenotype, which was similar to stem cells state in neuroblastoma." (PMID 24222909, 2013). "In addition, consistent with the cell cycle results, SP141 treatment led to decreased expression of Cdc2 and Cdc25A in both NB-1643 and LA1-55n neuroblastoma cells." (PMID 33291373, 2020).
retinoblastoma (5 papers, 2014 to 2022). A malignant tumor that originates in the nuclear layer of the retina. "They experimentally demonstrated that let-7b was down-regulated in retinoblastoma and the target mRNAs of let-7b, such as CDC25A and BCL7A, were over-expressed." (PMID 28793339, 2017). "CDC25A expression showed significant correlation with poor tumor differentiation and tumor invasion in retinoblastoma." (PMID 29246203, 2017).
acute myeloid leukemia (4 papers, 2015 to 2025). Acute myeloid leukemia (AML) is a group of neoplasms arising from precursor cells committed to the myeloid cell-line differentiation. "Previous studies have implicated miR-122-5p and CDC25A in a range of cancers, including hepatocellular, breast, and acute myeloid leukemia." (PMID 41373559, 2025). "Known for its oncogenic properties, CDC25A has been frequently observed in various cancer types, including lung cancer, breast cancer, and acute myeloid leukemia (AML), and is closely associated with poor patient prognosis." (PMID 41373559, 2025). "We recently identified the CDC25A phosphatase as a key actor in proliferation and differentiation in acute myeloid leukemia expressing the FLT3-ITD mutation." (PMID 32024878, 2020). "In this work we investigated the molecular mechanisms that control CDC25A transcription and translation in acute myeloid leukemia cells that express the FLT3-ITD mutant tyrosine kinase receptor." (PMID 32024878, 2020). "Although miR-122-5p and CDC25A have been studied in several malignancies such as hepatocellular carcinoma and acute myeloid leukemia, their coordinated regulatory relationship within the molecular context of BCR::ABL1-positive chronic myeloid leukemia has not been previously characterized." (PMID 41373559, 2025).
bladder cancer (4 papers, 2017 to 2022). "In addition, TACC3 is highly co-expressed with MCM4, CDC6, and CDC25A, indicated by correlation analysis using RNA-seq data of 42 bladder cancer clinical samples from our group published before." (PMID 29358577, 2018). "Four genes (BUB1B, CCNB1, CDC25A and NDC80) were expressed at higher levels in bladder cancer tissues than in normal bladder tissues, but the expression of FBXO5 was lower in bladder cancer than in normal tissues." (PMID 29246203, 2017). "To evaluate the significance of the five proteins in bladder cancer, we investigated the relationship between the expression of the five proteins (BUB1B, CCNB1, CDC25A, FBXO5, NDC80) and clinicopathological features." (PMID 29246203, 2017). "We performed protein-protein interaction analysis to select five important candidate genes (BUB1B, CCNB1, CDC25A, FBXO5, KIF20A, NDC80) regulated by PLK1 in bladder cancer cells using STRING software." (PMID 29246203, 2017).